ZNF718 (zinc finger protein 718)
Description:
May be involved in transcriptional regulation.
Synonyms: FLJ90036
Tractability: PROTAC: ubiquitination databases record sites on it.
Gene: Protein-coding gene on chromosome 4 (124,501 to 202,303, forward strand). Ensembl gene ENSG00000250312.
Subcellular location: Nucleus
Pathways (Reactome):
Gene expression (Transcription): Generic Transcription Pathway
Gene Ontology:
Molecular function: DNA-binding transcription factor activity, RNA polymerase II-specific; RNA polymerase II cis-regulatory region sequence-specific DNA binding
Biological process: regulation of DNA-templated transcription; negative regulation of transcription by RNA polymerase II
Cellular component: nucleus
Genetic constraint (gnomAD): Loss-of-function variants: 2 observed, 1.45 expected, observed/expected ratio (o/e) 1.38, 90% interval 0.44 to 1.92. That is too few expected variants to judge how well the gene tolerates losing a copy.
Homologues: Orthologues: chimpanzee ZNF718 (99% identical). Paralogues in human: ZNF595 (71% identical), ZNF141 (68% identical), ZNF732 (66% identical), ZNF493 (63% identical), ZNF708 (60% identical), ZNF728 (59% identical), ZNF254 (58% identical), ZNF724 (58% identical), ZNF726 (58% identical), ZNF429 (57% identical), ZNF43 (55% identical), ZNF85 (54% identical), and 164 more.
Diseases named in the same sentence as ZNF718 in open-access papers:
ZNF718 is named in the same sentence as 7 diseases in open-access papers, as found by Europe PMC text mining. Sharing a sentence is not in itself a finding about the gene and the disease. The quoted sentences say what the papers report.
herpes simplex infection (1 paper, 2021). "Our study identified DE TFs such as ZNF180, ZNF763, ZNF792, ZNF718, and ZNF461 associated with asthmatic ASM cells and enriched for the herpes simplex infection pathway." (PMID 34257337, 2021).
ZNF718 also shares sentences with these, for which no sentence is quoted: diabetes (2 papers); asthma (1); cancer (1); head and neck squamous cell carcinoma (1); metabolic disease (1); periodontitis (1).